ARID2 (AT-rich interaction domain 2)
Diseases named in the same sentence as ARID2 in open-access papers (continued):
Sharing a sentence is not in itself a finding about the gene and the disease.
melanoma (continued). "Another exome sequencing study described six novel melanoma genes: PPP6C, RAC1, SNX31, TACC1, STK19, and ARID2." (PMID 25393105, 2014). "While Arid2 loss can result in genomic redistribution of BAF in melanoma, this is unlikely to occur in DMTF1 KD NSC given that DMTF1 loss down-regulates both Ss18 and Arid2 expression." (PMID 41481722, 2026). "Similarly, mutations in the components of the SWI/SNF chromatin remodeling complex, such as AT-rich interactive domain-containing protein 2 (ARID2) and ATRX Chromatin Remodeler (ATRX) have been identified in melanoma samples." (PMID 40554927, 2025). "Loss-of-function mutations in the components of the SWI/SNF complex such as AT-rich interactive domain-containing protein 1A (ARID1A), ARID1B, ARID2, or SMARCA4 are common in melanoma, suggesting that altered chromatin remodeling plays a role in the pathogenesis of this disease." (PMID 36844227, 2023). "Functional studies suggest that ARID2 does not affect melanoma proliferation but instead suppresses melanoma invasion in vitro." (PMID 35323214, 2022). "The biological impact of alterations in other epigenetic regulators, such as ARID2 which occurs at a high frequency in melanomas, are lacking, and further research is essential to illustrate their role in melanomagenesis." (PMID 34831002, 2021). "Loss-of-function mutations in the SWI/SNF complex components such as AT-rich interactive domain-containing protein 1A (ARID1A), ARID1B, ARID2, or SMARCA4 are frequent in melanoma, suggesting that altered chromatin remodeling plays a role in the pathogenesis of this disease." (PMID 34440824, 2021). "Inactivation of three genes, including polybromo 1 (PBRM1), AT-rich interaction domain 2 (ARID2), and bromodomain containing 7 (BRD7), that code for PBAF, one of the chromatin-remodeling complexes of the SWI/SNF, sensitized melanoma cells for destruction by T cells." (PMID 34827646, 2021). "A genome-scale CRISPR-Cas9 screen has identified the inactivation of ARID2, BRG1, and BRD7—all of which are members of the PBAF form of the SWI/SNF complex—to be responsible for the sensitization of melanoma murine models to cytotoxic T-cells via an enhanced response to IFN-gamma." (PMID 34440824, 2021). "Although not as frequently mutated in melanoma as ARID2 and SMARCA4, PBRM1 protein levels are highly sensitive to the levels of SMARCA4 protein and incorporation into the SWI/SNF complex requires the presence of ARID2." (PMID 35323214, 2022). "Moreover, we detected single nucleotide transitions in ARID1A, ARID2, SMARCA4 and BAP1, all genes which have not been associated before with CNS metastases of melanomas." (PMID 33578810, 2021). "Interestingly, we identified variants in five new candidate genes, i.e., ARID1A, ARID2, SMARCA4, PIK3R1 and BAP1, which neither have been previously identified in melanoma BM nor reported in CNS metastases from other cancers." (PMID 33578810, 2021). "Consistent with the TCGA analysis, PBRM1 mutations were most common in ccRCC patients (46.6%), followed by non-melanoma skin cancer (9%) and melanoma (8%), while ARID2 was most common in melanoma (13%), followed by non-melanoma skin cancer and colorectal cancer (11%)." (PMID 32820162, 2020).
hepatocellular carcinoma (36 papers, 2011 to 2026). A malignant tumor that arises from hepatocytes. "ARID2 mutations were first recognized in hepatocellular carcinoma (HCC), followed by colorectal cancer." (PMID 39054516, 2024). "There are reports of ARID2 loss-of-function mutations in a wide variety of human malignancies, such as melanoma, gastric adenocarcinoma, non-small cell lung cancer and hepatocellular carcinoma, suggesting its tumour suppressor function." (PMID 39471843, 2024). "Mutations or alterations in the ARID2 gene have been implicated in different cancers, such as hepatocellular carcinoma, ovarian cancer, colorectal cancer, and lung adenocarcinoma." (PMID 38023196, 2023). "In several studies, ARID2 mutations and/or lower protein expression of ARID2 have been reported to correspond to poor patient prognosis in hepatocellular carcinoma, intrahepatic cholangiocarcinoma, breast cancer, oral SCC, and lung cancer." (PMID 37244956, 2023). "Mechanistic studies on the role of ARID2 in hepatocellular carcinoma and lung cancer have shown that an ARID2 loss drives transcriptional reprogramming and impairs the DNA-damage response pathways." (PMID 33941852, 2021). "ARID2 knockout results in dysfunction of DNA repair process, leading to susceptibility to carcinogens in human hepatocellular carcinoma cells." (PMID 33880365, 2021). "ARID2 has been suggested to be tumor suppressive in hepatocellular carcinoma, with a mutation rate of 6.5%." (PMID 27270314, 2016). "A recent study revealed that 18.2% of patients with HCV-associated hepatocellular carcinoma have inactivating mutations in ARID2." (PMID 26634163, 2015). "ARID2 mutations were enriched in clusters 1–2 with greater methylation changes, and a previous study in hepatocellular carcinoma indicates that ARID2 could recruit DNMT1 to the promoter, which increased promoter methylation." (PMID 35130881, 2022). "ARID2 is frequently mutated in non-small cell lung carcinoma and hepatocellular carcinoma." (PMID 33941852, 2021). "In addition to NOTCH2, mutations in ARID2, a possible tumor suppressor, are also found in hepatocellular carcinomas." (PMID 31480474, 2019). "Mutation of another PBAF component, BAF200/Arid2, is found in hepatocellular carcinoma." (PMID 22336179, 2012). "ARID2 mutations were first identified in hepatocellular carcinoma (HCC) which suggested a tumor suppressive activity." (PMID 32977645, 2020). "Given the high prevalence of APC and ARID2 mutations in other gastrointestinal tumors such as colorectal cancers and hepatocellular carcinomas instead of gastric adenocarcinomas, this finding suggests that gastric adenoma may represent a disease category distinguished from gastric adenocarcinomas." (PMID 27175599, 2016). "ARID2 is required for activation of a subset of IFNα-induced genes in hepatocellular carcinoma (HCC)." (PMID 34865122, 2021). "In this review, we summarize what we know about the tumor-modulating properties of ARID2 in hepatocellular carcinoma." (PMID 32977645, 2020). "In HBV-related HCC, the HBV X protein is reported to suppress ARID2 expression, leading to increased hepatoma tumorigenesis." (PMID 30521023, 2018). "In hepatocellular carcinoma, ARID2 represses EMT by recruiting DNMT1 to suppress SNAI138." (PMID 35945219, 2022). "By querying the OncoKB database for genes located at 12q12, only ARID2 deletion was found to be likely oncogenic, specifically in non-small cell lung cancer and hepatocellular carcinoma; in our analysis, ARID2 whole gene deletion co-occurred in 14.53% of LRRK2 CNV-altered cases." (PMID 32722212, 2020). "In addition, restoring ARID2 expression in hepatoma cells suppressed cell growth and tumor progression in mice while ARID2 inhibition resulted in upregulation of cell cycle proteins such as cyclin D1 and cyclin E1, suggesting a tumor suppressive role for ARID2 in HCC." (PMID 31056726, 2019).
hepatocellular carcinoma (continued). "ARID2 is a member of the AT-rich interactive domain (ARID) family, which affects diverse cancer types, including gastric cancer, PCa, oral squamous cell carcinoma non-small cell lung cancer, sporadic rectal cancer and hepatocellular carcinoma." (PMID 40297177, 2025). "Moreover, a cooperative manner of frequent joint inactivation of ARID2, PBRM1 and BAP1 in the subtype of hepatic carcinomas may contribute to malignancy." (PMID 36178086, 2022).
non-small cell lung carcinoma (12 papers, 2015 to 2025). A group of at least three distinct histological types of lung cancer, including non-small cell squamous cell carcinoma, adenocarcinoma, and large cell carcinoma. "In a very recent study, a higher sensitivity to different DNA-damaging therapies in ARID2-deficient non-small cell lung cancer cells, likely as a result of the ARID2 involvement in DNA repair, was observed." (PMID 32850962, 2020). "Moreover, higher sensitivity to different DNA-damaging therapies has been observed ARID2-deficient non-small cell lung cancer cells, likely due to ARID2 involvement in DNA repair." (PMID 36901733, 2023). "Some studies revealed frequent inactivating mutations in ARID2 in unstable colorectal cancer and non-small cell lung carcinoma, Loss of ARID2 expression also existed during the progression of gastric cancer and hepatocellular, ARID2 took part in the important pathway genes in pancreatic cancer too." (PMID 33592583, 2021). "When univariately examining LOF mutations in PBRM1 and ARID2 as well as LOF in PBRM1 alone, they remained significantly associated with adverse OS in non-small-cell lung cancer." (PMID 32820162, 2020). "Given the higher frequency of ARID2 mutations in the non-RCC cohorts, we combined PBRM1 and ARID2 LOF and non-LOF mutations for individual subtype analysis, which was significant in non-small-cell lung cancers." (PMID 32820162, 2020).
colorectal cancer (11 papers, 2015 to 2024). A primary or metastatic malignant neoplasm that affects the colon or rectum. "Exome sequencing has uncovered frequent inactivating mutations in the AT-rich interaction domain 2 (ARID2) in microsatellite unstable colorectal cancer." (PMID 37298127, 2023). "According to the results of the pan-cancer analysis, we found that the abundances of CD4 + T cells and CD8 + T cells were significantly elevated in the mutated ARID1A, mutated ARID1B and mutated ARID2 groups, especially for colorectal cancer and gastric cancer." (PMID 35239432, 2022). "ARID2 is mutated in 13% of colorectal cancer patients with microsatellite instability." (PMID 27270314, 2016). "ARID2 could function as a tumour suppressor gene in colorectal cancer and constitute an important downstream element in the regulatory pathway of TGF-β in LIHC." (PMID 35127746, 2021). "In addition, we found that silencing MUC1-C in (i) NCI-H660 neuroendocrine PC (NEPC) cells, (ii) BT-549 triple-negative breast cancer and (ii) SW620 colorectal cancer (CRC) cells results in downregulation of PBRM1, ARID2, and BRD7." (PMID 34163028, 2021).
liver cancer (8 papers, 2014 to 2025). An epithelial or non-epithelial malignant neoplasm that arises from the liver. "The CREB1/miR-922/ARID2 axis promoted liver cancer progression, with miR-922 targeting ARID2, while ARID2 overexpression counteracted malignancy." (PMID 40074445, 2025). "Additionally, human liver cancer cell line SNU-398 (ARID2 mutant) was more sensitive to KNK437 than HepG2 (ARID2 wild-type)." (PMID 34858604, 2021). "Thus, HNF4A is likely to be a novel driver gene for liver cancer, as well as ARID2 and RPS6KA3." (PMID 25526364, 2014). "While ARID4A is not described in COSMIC or previous sequencing studies of liver cancer, recurrent mutations in the paralogous nucleosome remodelers ARID1A, ARID1B, and ARID2 have been previously reported in HCC21,30,35." (PMID 31796844, 2019).
lung carcinoma (8 papers, 2017 to 2023). "High frequency of ARID2 mutation has been documented in different types of human cancers including lung cancer." (PMID 34858604, 2021). "ARID2 deficiency has been linked to PARPi sensitivity in lung cancer." (PMID 37575280, 2023). "In addition, knockdown of ARID2 accelerated tumor progression in lung cancer and ARID2 deficiency was associated with higher sensitivity to chemotherapy." (PMID 36567903, 2022). "Treatment with an HSPA1A inhibitor could significantly inhibit the malignant progression of lung cancer with ARID2 deficiency." (PMID 34858604, 2021). "Furthermore, HspA1A specifically inhibits the malignant progression of Arid2-deficient lung cancer." (PMID 35887223, 2022). "USP2 exhibited inhibitory effects on lung cancer cell malignancy via ARID2 de-ubiquitination and protein degradation inhibition." (PMID 36567903, 2022). "In this study, we demonstrated that knockdown of ARID2 greatly promoted the migration and invasion of lung cancer cells, which is in line with previous research." (PMID 36567903, 2022). "Functional experiments suggested USP2 inhibited lung cancer cell invasion and migration by reducing ARID2 protein degradation." (PMID 36567903, 2022). "In this study, we first demonstrated that USP2 inhibited the malignancy of lung cancer by reducing ARID2 protein degradation via ubiquitination." (PMID 36567903, 2022). "USP2 significantly inhibited lung cancer by interacting with ARID2 and reducing ARID2 protein degradation via ubiquitination." (PMID 36567903, 2022). "The results indicated that in both A549 and H1299 cells, ARID2 protein can be detected in anti-USP2 antibody precipitated protein samples, and vice versa, suggesting endogenously USP2-ARID2 protein-protein interaction (PPI) in lung cancer cells." (PMID 36567903, 2022). "To evaluate the role of ARID2 in the pathogenesis of autochthonous mouse models of lung cancer, we first crossed the Arid2fl/fl mice to K mice to generate the KrasG12D/+Arid2fl/fl (KA) mice." (PMID 34858604, 2021). "Consistently, ARID2 knockdown significantly promotes cell proliferation in human and mice lung cancer cells." (PMID 34858604, 2021). "Using two KrasG12D-based genetically engineered murine models, we demonstrate that ARID2 knockout significantly promotes lung cancer malignant progression and shortens overall survival." (PMID 34858604, 2021). "Histopathological analyses confirmed that ARID2 deletion greatly promoted the malignant progression of lung cancer in K mice." (PMID 34858604, 2021). "Using clinical specimens and autochthonous mouse models of lung cancer, we provide strong evidence to illustrate a tumor suppressive role of ARID2 in LUADs." (PMID 34858604, 2021). "No substantial difference in the positive staining of cleaved-caspase-3 (CC-3) was observed between the ARID2-knockdown and control groups, indicating that ARID2 mainly suppresses proliferation of lung cancer cells." (PMID 34858604, 2021). "Using autochthonous mouse models of lung cancer, we demonstrated a tumor suppressive role of ARID2 in LUADs." (PMID 34858604, 2021). "A previous study indicated that ARID2 deficiency could damage DNA repair and enhance the sensitivity of the cells to DNA-damaging agents, and ARID2 played a tumor suppressor role in lung cancer progression." (PMID 36567903, 2022). "Our study provided novel insight that USP2 might suppress lung cancer by reducing ARID2 protein degradation via ubiquitination." (PMID 36567903, 2022). "Lung cancer patients with ARID2 deficiency may also benefit from PARP inhibition, as PARP inhibitor veliparib has been shown to reduce cell survival of certain lung cancer cell lines." (PMID 33941852, 2021). "Knockdown of Hspa1a specifically inhibits malignant progression of Arid2-deficient but not Arid2-wt lung cancers in both cell lines as well as animal models." (PMID 34858604, 2021).
lung carcinoma (continued). "The results of our study further expand the regulatory function of ARID2 in lung cancer cell invasiveness and EMT process and suggest the potential of the USP2-ARID2 axis as a novel target in future therapy development for lung cancer." (PMID 36567903, 2022). "In the old lung cancer group, there were genes significantly concurrent with actionable driver genes (CDKN2A, NF1): FAT1, LRP1B, ARID2 with CDKN2A; EPHB1 with NF1, and genes significantly exclusive with actionable driver genes (EGFR, KRAS): MLL2, STK11, KRAS with EGFR." (PMID 35096611, 2021). "However, if USP could regulate lung cancer through targeting ARID2 has not been reported." (PMID 36567903, 2022).
Coffin-Siris syndrome (7 papers, 2021 to 2025). "Patients with a mutation in ARID2 show similar but weaker phenotypes to Coffin-Siris syndrome, suggesting that ARID2 works cooperatively with cBAF in brain development or shares target sites with cBAF but regulates those independent of cBAF." (PMID 39541575, 2025). "The mosaic LoF variant in ARID2 in BD, which causes Coffin-Siris syndrome if it exists as a germline variant, is a notable example of this paradigm." (PMID 37248276, 2023). "Of note, one BD proband had an LoF mDNV in ARID2 (p.Arg1769*), a recurrent variant observed in multiple patients with Coffin-Siris syndrome as germline variants (ClinVar Accession: VCV000451913.4)." (PMID 37248276, 2023). "However, ARID2 mutants also affect brain development in some patients with intellectual defects, such as the NicolaidesBaraitser syndrome and the Coffin-Siris syndrome-like phenotype." (PMID 39541575, 2025).